LAG3 (lymphocyte activating 3)
Diseases named in the same sentence as LAG3 in open-access papers (continued):
Sharing a sentence is not in itself a finding about the gene and the disease.
tumor (continued). "Furthermore, immune checkpoint molecules including LAG3, PD-1, and TIM3 were significantly higher on tumor infiltrating lymphocytes of high grade compared to low grade tumors." (PMID 38691575, 2024). "In addition, overexpression of checkpoint molecules such as LAG-3 and TIM-3 on various immune cells also promotes tumor resistance to immunotherapy." (PMID 38673829, 2024). "Notably, LAG-3+TIM-3hi NK cells were progressively increased over time, suggesting that the tumor microenvironment exacerbated NK cell dysfunction." (PMID 38375265, 2024). "Therefore, we believe that ZGGS15 is expected to block LAG-3 and TIGIT in immune cells binding to their ligands to exert anti-tumor activity." (PMID 38724599, 2024). "In both datasets, LAG3 was found to be expressed mainly on exhausted CD8+ T cells (CD8Tex cells) rather than on tumor cells or other types of immune cells compared and was also co-expressed with PDCD1." (PMID 38277212, 2024). "LAG-3 expression correlates with PD-1 expression on TILs, suggesting implications for postoperative recurrence in non-small-cell lung cancer (NSCLC) and compromised anti-tumor responses in gastric cancer." (PMID 38785789, 2024). "Our experiments showed that knockdown of circRHBDD1 increased the percentage and number of CD8+ T cells in tumor tissues, along with elevated expressions of cytokines IFN-γ, TNF-α, and granzyme B, and reduced levels of coinhibitory molecules PD-1, TIM-3, and LAG-3." (PMID 39080693, 2024). "Although some clinical trials have demonstrated the anti-tumor potential of LAG-3 inhibitors, not all patients benefit from them." (PMID 39743998, 2024). "Overall, our data indicate that LAG-3, TIM-3, or 2B4 disruption not only prevents the upregulation of additional inhibitory molecules and enhances the cytotoxic activity upon chronic stimulations, but also supports a prolonged anti-tumor activity." (PMID 38510235, 2024). "In models where CIITA, the master regulator of MHC-II, is expressed, dual anti-LAG-3/PD-1 ICI treatment has exhibited profound antitumor effects and inhibited tumor growth in mice, resulting in stronger IFN-γ production and enhanced cytotoxicity of CD8+ T cells." (PMID 39743998, 2024). "This is in line with our observations, that immune cells in the TIME of HLA-G high MIBC – especially of evasion phenotype MIBCs- exhibited an upregulation of crucial immune checkpoint proteins like TIGIT, PD-L1, LAG3, and CTLA-4 on tumor cells (PD-L1) and immune cells (all proteins)." (PMID 39469714, 2024). "Initial studies demonstrated its ability to impede HCC progression, while recent findings have identified FGL1 as a functional ligand of lymphocyte activation gene 3 (LAG-3), thereby promoting HCC progression through modulation of the tumor microenvironment (TME)." (PMID 38816776, 2024). "In addition, IHC staining for exhaustion markers, including LAG-3, TIGIT, and TIM-3, was conducted on the tumor tissues to evaluate their impact on T cell exhaustion." (PMID 39459546, 2024). "In our study, we found that high PSMB2 expression may induce the upregulation of CD274, CTLA4, HAVCR2, LAG3, PDCD1, PDCD1LG2 and SIGLEC15, which are molecules on immune cells that facilitate tumor immune escape." (PMID 38467767, 2024). "The anti-tumor effects of CD8+T cells could also be enhanced by blocking inhibitory immune checkpoints such as PD-1, PD-L1, CTLA4, and LAG3." (PMID 38853203, 2024). "This indicated that the increased LAG-3 expression induced by GEM in vivo was restricted to tumor-antigen specific CD8+ TPEX in DLNs but not in tumors." (PMID 39343508, 2024). "Unfortunately, in the TME, these checkpoints, such as CTLA-4, programmed death receptor–1 (PD-1), Nectin-4, and lymphocyte activation gene 3 (LAG3) on T cells, are engaged with their partner ligand on tumor cells to downregulate immune response, leading to reduced cytotoxicity." (PMID 39201585, 2024).
tumor (continued). "Our study identified PD-1, LAG-3, and TIM-3 as promising targets of a therapeutic strategy targeting the tumor microenvironment in HNSCC, particularly among HPV-positive patients, where a higher expression of these checkpoints correlated with an improved overall survival." (PMID 39769271, 2024). "LAG-3 hinders effective recognition and clearance of tumor cells by NK cells through interaction with FGL1 (fibrinogen-like protein), which is highly expressed in hepatocytes and tumor cells." (PMID 39906665, 2024). "In addition, we further validated the expression patterns observed in our transcriptomic analysis, identifying increased expression of LAG-3 and CD69 as characteristic features of the CD49a+ ‘tumor -retained’ state." (PMID 38267402, 2024). "Tex cells exhibit elevated inhibitory receptors (PD-1, CTLA-4, TIM-3, TIGIT, LAG-3), reduced antitumor cytokines (IFN-γ, IL-2, TNF), increased tumor-promoting chemokines, altered transcription factors (TCF1, T-bet, TOX), metabolic issues, and decreased proliferation and survival." (PMID 39717767, 2024). "Moreover, several ICPs such as Lag-3 and TIGIT were up-regulated in NK cells from tumor-bearing mice." (PMID 39196934, 2024). "To prove that the co‐localization promotes T cell exhaustion, we co‐cultured ALCAMhigh macrophages and ALCAMlow macrophages from human or mouse CRC tumor with T cells separately, then using FACS to assess the expression levels of exhaustion markers (PD‐1 and LAG3) in T cells." (PMID 38956900, 2024). "In the tumor microenvironment, CD8+ T cells have been shown to be functionally exhausted with impaired proliferation, secretion of inflammatory cytokines, and expression of markers such as PD-1, Tim3, Lag3, Slc16a11, CD49b, Tox, and others." (PMID 39320047, 2024). "This heightened immune cell presence is consistent with the observed reduction in exhaustion markers, such as LAG-3, TIGIT, and TIM-3, emphasizing the potential of BJIKT and pembrolizumab to mitigate T cell exhaustion and sustain a robust anti-tumor immune response." (PMID 39459546, 2024). "Lymphocyte-activation gene 3 (LAG-3), a co-inhibitory receptor that highly expresses on various immune cells, binds to MHC (major histocompatibility complex) class II molecules expressed by tumor cells to negatively regulate the anti-tumor immunity." (PMID 38673829, 2024). "We found several molecules that are significant in tumor initiation and treatment by immune checkpoint analysis, such as lymphocyte-activation gene 3 (LAG3), PTPRC, HAVCR2, B2M, LDHA, and LDHB, which may be used as a reference for tumor immunotherapy." (PMID 39014082, 2024). "In addition, tumor cDCs from patients with HCC were found to express inhibitory ligands such as PD-L1, Gal9 (ligand for TIM3), MHC-II (LAG3), CD86 and CD80 (CTLA-4)." (PMID 39146202, 2024). "The anti-LAG-3 antibody is useful in inhibiting the interaction of LAG-3-expressing CD8 T cells with corresponding ligands on tumor cells, facilitating activation, and killing the tumor cells on the CD8 T cells." (PMID 39796650, 2024). "The feasibility of this approach was demonstrated by the ability of IMP321, a soluble LAG-3 fusion protein capable of binding to MHC-II, to inhibit tumor growth in vivo, significantly activating CD8+ T cells, and extending PFS in patients with advanced renal cancer." (PMID 39660130, 2024). "Analysis of spleens of mice isolated 13 days after transplantation confirmed the previously observed greater T-cell recruitment and increased expression of the exhaustion markers PD-1, TIGIT, LAG3 and TIM3, despite the reduced tumor burden in mice that received NFKBIE-ko cells." (PMID 38486128, 2024). "Though the anti-LAG-3 group had a lower mean tumor burden than IgG isotype controls, this difference was not statistically significant (p = 0.8006)." (PMID 39623404, 2024).
tumor (continued). "Furthermore, the mLAG-3-specific Nb 3132 was able to quantify dynamic LAG-3 expression within the TME and tumor-draining lymph nodes of PD-1-treated MC38 tumor-bearing mice, revealing a compensatory LAG-3 upregulation as a consequence of PD-1 blockade." (PMID 39281708, 2024). "In previous work, treating orthotopic 3LL lung tumors with KRAS-G12C inhibitors only provided temporary tumor control, and combinations with anti–PD-1 or anti–PD-L1 and anti-LAG3 failed to give additional benefit." (PMID 39485838, 2024). "Two of these patients showed objective responses with a tendency to convert an immune-cold into an immunoactive biomarker on tumor biopsies, and another early targeting strategy for LAG-3 involved the bispecific monoclonal antibody tebotelimab (MGD013), which cotargeted LAG-3 and PD-1." (PMID 38581716, 2024). "The expression of LAG-3 is under the control of various transcription factors that are, in part, regulated by the CD8 T cell receptors binding to the corresponding MHC-I peptide complex on the tumor cells." (PMID 39796650, 2024). "When assessing tumor-infiltrating exhausted CD8+ T cells with exhaustion unique gene markers, such as Lag3, Tigit, Havcr2, Ctla4, and Pdcd1, we observed that the Lag3 and Tigit levels in the MnBuOE/RT group were significantly lower than those in the other groups (p < 0.05)." (PMID 38671924, 2024). "Upon triple knockdown of exhaustion markers (PD-1, Tim-3, and Lag-3), CAR-T cells, which target the preS1 domain of HBsAg and exhibit the tumor-reactive marker CD39+ (preS1-CAR-T), potently inhibit tumor growth and increase IFNγ secretion in a patient-derived xenograft (PDX) mouse model." (PMID 39075601, 2024). "LAG-3 is highly expressed by tumor-infiltrating lymphocytes in cancer and represents a non-immunoreceptor inhibitory receptor with a tyrosine-based inhibitory motif." (PMID 38280005, 2024). "Importantly, only CD8 T cell depletion completely abrogated the anti-tumor efficacy of the triple PD-1/LAG-3/CBL-B blockade combination both in terms of survival and tumor growth." (PMID 39030301, 2024). "However, subsequent investigations revealed its potential to inhibit the LAG3/MHC-II interaction, thereby enhancing T cell-mediated cytotoxicity and suppressing tumor cell proliferation." (PMID 39743998, 2024). "Interestingly, XBP1 can simultaneously regulate the expression of multiple immune checkpoint molecules, such as PD1, LAG3, and HAVCR2, in some types of tumours, suggesting that XBP1 is a potential target for overcoming immunotherapy resistance." (PMID 38297380, 2024). "Given that ADAM17-mediated substrate cleavage is highly dependent on the biological context, the regulation of Lag-3 and Tim-3 by ADAM17 in tumor-infiltrating CD8+ T cells might have more complex mechanisms." (PMID 38918390, 2024). "Additionally, we observed that the spatial distribution of TILs co-expressing PD1 with LAG3 and/or TIM3 and/or TIGIT influences outcomes, with closer proximity to tumor cells indicating worse clinical benefit." (PMID 39591972, 2024). "The pro-tumor microenvironment of CLL is already sustained by suppressive soluble factors (e.g., IL-10, TGF-β) and inhibitory immune molecules (e.g., PD-L1, LAG3), among which the tolerogenic milieu would only be compounded by therapeutics that induce immunosuppressive DAMP release from CLL cells." (PMID 39767763, 2024). "No correlative trends were observed between clinical response and immunohistochemistry expression scores of LAG-3, PD-1, or MHC class II, likely due to the small number of patients, low objective response rates, multiple tumor types, and different dose levels tested." (PMID 39422598, 2024). "Normal mLN NK cells did not express LAG-3 or TIM-3, whereas mLN NK cells of tumor-bearing mice expressed higher LAG-3 and TIM-3 to generate two NK subsets: LAG-3+TIM-3hi NK cells and LAG-3-/loTIM-3-/lo NK cells." (PMID 38375265, 2024).
tumor (continued). "Besides PD-1, CTLA4, and LAG3, other immune checkpoint molecules like TIM3 and TIGIT have also been identified as potential tumor-agnostic targets for T-cell-mediated cancer immunotherapy." (PMID 38920700, 2024). "We previously performed spatial proteomic profiling on overlapping samples from the RCC TMAs to characterize expression patterns of multiple tumor immunomarkers, including CD3, PD-1, PD-L1, LAG3, TIM-3, and CTLA-4 in immune cells (CD45+), and PD-L1 in tumor cells (CK+)." (PMID 39105820, 2024). "Moreover, the expression of ADAM10 was reciprocally exclusive with some tumor immune checkpoint genes, such as VEGFB, LAG3, IL4, TNFRSF18, TNFRSF4, TNF receptor superfamily member 14 (TNFRSF14), CD27, CCL5, etc.." (PMID 39211038, 2024). "Although the role of LAG-3 has not been clarified, it is believed to be involved in the inhibition of T cell proliferation and activation, and is expressed on tumor-infiltrating T cells, T cells exhausted by chronic infection, and regulatory T cells." (PMID 38668032, 2024). "Adjacent T-cell-rich regions had higher levels of key proteins such as CD45RO and several immune suppressive factors (IDO1, VISTA, TIM-3, LAG-3 and ICOS), which may result in less T-cell expansion in regions close to the tumor." (PMID 39001353, 2024). "Additionally, the activation gene-3 (LAG3) and immunoglobulin and mucin domain protein 3 (TIM3) were highly found in Tumor-infiltrating lymphocytes (TILs) in TNBCs." (PMID 38397971, 2024). "It has been illustrated that the binding of LAG3 to the primary ligand MHC class II results in the repression of effector T cells like PD-1 and increases the regulatory T cell activity, thereby supporting tumor growth." (PMID 38255322, 2024). "Lymphocyte activation gene-3 (LAG-3), T-cell immunoglobulin and mucin-containing protein-3 (TIM-3) and OX-40 are less reported immunoadjuvant molecules, but they are equally involved in the regulation of tumor cell immunity." (PMID 39329710, 2024). "The immune analysis results show that high-expression of DLD may reduce T cell-mediated anti-tumor immunity by regulating immune infiltration of CD8 + T cells and positively regulating immune checkpoints LAG3 and CD276." (PMID 38581529, 2024). "DLD’s high expression may therefore reduce T cell-mediated anti-tumor immunity by regulating CD276 and immune checkpoints LAG3 positively and regulating CD8 + T cells’ immune infiltration." (PMID 38581529, 2024). "We hypothesized that the inhibition of LAG-3 expression, by inhibiting its regulation by YY1, offers an alternative to CPIs that could lead to the restoration of the anti-tumor CD8 T cell function and be effective in cases of resistance to CPIs." (PMID 39796650, 2024). "Further exploration of treatments targeting other immune checkpoints, including LAG-3, VISTA, TIGIT, TIM-3, ADORA2, as well as therapies involving TIL (tumor-infiltrating lymphocytes), holds promise for delivering survival benefits to this subgroup of patients." (PMID 38469235, 2024). "Tumor-infiltrating PDCD1+ and LAG3+ cells expressed CBLB, while a minor proportion expressed CBLC." (PMID 39030301, 2024). "Through immunofluorescence experiments, we observed that LAG3 expression is observed in immune cells (CD45+ cells) rather than in tumor cells (PAX8+ cells)." (PMID 38277212, 2024). "For example, mAbs targeting the programmed death receptor axis PD-1/PD-L1, T cell immunoglobulin and ITIM domain (TIGIT), lymphocyte activation gene-3 (LAG-3), and T cell immunoglobulin mucin-3 (TIM-3) are known to enhance NK cell function and improve anti-tumor responses." (PMID 38545115, 2024). "Furthermore, the proportion of T-cells transduced with FGFR4.28HTM.28z-CD276.8HTM.BBz BiCisCAR that expressed exhaustion markers was significantly lower within tumor (CD39 and Tim-3) and in the blood (CD39 and LAG-3) compared to those observed with other CARs." (PMID 39043633, 2024).
tumor (continued). "However, tumor-infiltrating CD8+ T cells obviously reduced the expression of exhaustion markers (PD-1 and LAG3) in Rab37 KO tumors." (PMID 38321486, 2024). "In contrast, M-MDSC and PMN-MDSC rapidly dropped after the first treatment cycle, indicating a direct activity of LAG3/PD-1 blocking on the systemic myeloid population rather than an indirect effect due to the reduced tumor burden." (PMID 38336861, 2024). "Moreover, upon analyzing the TCGA database, which included 250 cancer patients treated with PD‐1/PD‐L1 inhibitors, the tumor microenvironment phenotype demonstrated a notable increase in PD‐1, TIM‐3, LAG3, TIGIT, T‐bet, and EOMES in tumors of obese patients." (PMID 38334504, 2024). "Additionally, a strong correlation between RHBDF2 upregulation and immune checkpoint genes (PDCD1, CD274, LAG3, CTLA4, TIGIT, HAVCR2) was observed in HCC, and these immune checkpoint genes can contribute to tumor immune escape and promote tumor progression." (PMID 36943228, 2023). "CD274 expression was found to be down-regulated in tumor tissues (P < 0.05), while TIGIT, PDCD1, CTLA4 and LAG3 expression in tumor tissues were not statistically different." (PMID 36959799, 2023). "In LUAD, multiple T-cell subsets (CD8+, CD45RO+, CD8+CD45RO+ and CD4+FoxP3+) showed closer proximity to tumour cells than in LUSC, which exhibited closer distances from tumour cells to T-cells expressing LAG-3, OX40 and TIM-3, and B-cells expressing OX40 and LAG-3." (PMID 37835491, 2023). "In the process of APOBEC mutagenesis, the increased expression of important immune checkpoint molecules, including PDCD1, TIGIT, HAVCR2, LAG3 and IDO1, and the elevated CYT score, which serves as cytotoxic effects and anti-tumor response, were highly suggestive of better immunotherapy response." (PMID 37215984, 2023). "Taken together, these results confirm that most of the LAG-3 expression in patients with solid tumors is found on tumor infiltrating, but not circulating, CD8 and CD4 memory T cells." (PMID 37795090, 2023). "We previously observed such an engagement of the complement system following treatment of the same tumor model with NBTXR3+XRT in tandem with checkpoint inhibitors of PD1, LAG3, and TIGIT — a treatment combination that yielded similarly impressive results to the therapy in this study." (PMID 37345658, 2023). "Furthermore, tumor-infiltrated CD8+ T and CD4+ T cells in the allografts highly expressed the activation/exhaustion markers, such as GZMB, GZMK, PDCD1, LAG3, HAVCR2, and CTLA-4." (PMID 37980406, 2023). "In this study, the anti-PD-1 antibody not only did not inhibit tumor growth, but it also led to the mice harboring many more T cells expressing PD-1, LAG-3, and TIGIT compared to the non-treatment mice." (PMID 37999131, 2023). "By contrast, these cells would be highly vulnerable to suppression within the TME given their expression of multiple inhibitory receptors (PD-1, TIM-3, LAG-3 and CD39), which could render them dysfunctional and unable mediate effective tumour control in situ." (PMID 37153625, 2023). "In addition, combining anti-LAG-3 mAbs with anti-PD-1 mAbs has been shown to enhance IFN-γ production and the cytotoxic capacity of T cells, leading to robust control of tumor growth." (PMID 37055849, 2023). "Because Tex cells within tumor bed express high levels of TIM-3 and LAG3, it is hypothesized that the combination of anti-PD-1/L1, anti-TIM-3 and anti-LAG3 treatment may reactivate Tex cells." (PMID 37881432, 2023). "Future studies may include combinations with lymphocyte-activation gene 3 (LAG-3) as this combination has been shown to act synergistically to restore function of exhausted T cells and promote tumor regression." (PMID 37796298, 2023). "As expected, we found that the majority of LAG-3 was expressed by tumor-infiltrating, but not circulating, CD8 memory T cells, with lower, but detectable, levels of LAG-3 on tumor-infiltrating CD4 T-helper cells and Tregs." (PMID 37795090, 2023).